TFAP4 (transcription factor AP-4)
Description:
Transcription factor that activates both viral and cellular genes by binding to the symmetrical DNA sequence 5'-CAGCTG-3'.
Synonyms: bHLHc41; AP-4
Tractability: PROTAC: UniProt records ubiquitination sites on it; ubiquitination databases record sites on it; its protein half-life has been measured.
Gene: Protein-coding gene on chromosome 16 (4,257,186 to 4,273,075, reverse strand). Ensembl gene ENSG00000090447.
Subcellular location: Nucleus
Subcellular location (Human Protein Atlas): Mitochondria; Nucleoplasm
Gene Ontology:
Molecular function: DNA binding; DNA-binding transcription activator activity, RNA polymerase II-specific; DNA-binding transcription factor activity, RNA polymerase II-specific; E-box binding; histone deacetylase binding; protein binding; protein homodimerization activity; sequence-specific DNA binding; sequence-specific double-stranded DNA binding; transcription cis-regulatory region binding; RNA polymerase II cis-regulatory region sequence-specific DNA binding; protein dimerization activity
Biological process: host-mediated activation of viral transcription; host-mediated suppression of viral transcription; negative regulation of cell population proliferation; negative regulation of cyclin-dependent protein serine/threonine kinase activity; negative regulation of DNA binding; negative regulation of DNA-templated transcription; positive regulation of apoptotic process; positive regulation of DNA-templated transcription; protein-containing complex assembly; regulation of mitotic cell cycle phase transition; regulation of transcription by RNA polymerase II; cellular response to dexamethasone stimulus; negative regulation of gene expression; positive regulation of transcription by RNA polymerase II
Cellular component: nucleoplasm; nucleus; chromatin; transcription repressor complex
Genetic constraint (gnomAD): Loss-of-function variants: 7 observed, 36.9 expected, observed/expected ratio (o/e) 0.19, 90% interval 0.11 to 0.36. The upper end of that interval is the gene's LOEUF score, 0.36, which puts it in group 1 of 6, group 1 being the genes least tolerant of losing a copy. Missense variants: 373 observed, 442.27 expected, observed/expected ratio (o/e) 0.84, 90% interval 0.77 to 0.92. Synonymous variants: 216 observed, 181.05 expected, observed/expected ratio (o/e) 1.19, 90% interval 1.07 to 1.34.
Homologues: Orthologues: chimpanzee TFAP4 (99% identical), macaque TFAP4 (99% identical), guinea pig TFAP4 (99% identical), mouse Tfap4 (98% identical), rat Tfap4 (98% identical), dog TFAP4 (97% identical), rabbit TFAP4 (93% identical), pig TFAP4 (88% identical), tropical clawed frog tfap4 (83% identical), zebrafish tfap4 (77% identical), Drosophila melanogaster crp (38% identical), Caenorhabditis elegans hlh-11 (30% identical). Paralogues in human: MLXIPL (22% identical), MLXIP (21% identical), MLX (13% identical).
Diseases named in the same sentence as TFAP4 in open-access papers:
TFAP4 is named in the same sentence as 32 diseases in open-access papers, as found by Europe PMC text mining. Sharing a sentence is not in itself a finding about the gene and the disease. The quoted sentences say what the papers report.
neuroblastoma (10 papers, 2016 to 2025). Neuroblastoma (NB) is the most common solid, extracranial childhood tumor. "We show for the first time that high expression of TFAP4 in primary neuroblastoma patients is associated with poor clinical outcome." (PMID 27448979, 2016). "To determine whether TFAP4 has prognostic significance in primary neuroblastoma, we analysed TFAP4 gene expression and its association with clinical outcome in an expression array dataset from a prospectively accrued primary neuroblastoma cohort of 649 patients (Oberthuer cohort)." (PMID 27448979, 2016). "Transcription factor activator protein 4 (TFAP4) is a key effector of MYCN amplification in neuroblastoma." (PMID 41244073, 2025). "TFAP4 is up-regulated and serves as an oncogene in various cancers, such as gastric cancer, neuroblastoma, and hepatocellular carcinoma." (PMID 34141611, 2021). "Overall, these results demonstrate that TFAP4 regulates proliferation in MYCN-amplified neuroblastoma." (PMID 29880876, 2018). "Silencing TFAP4 selectively inhibits MYCN-amplified neuroblastoma cell growth both in vitro and in vivo, in xenograft mouse models." (PMID 29880876, 2018). "To identify genes that are regulated by TFAP4 in MYCN-amplified neuroblastoma, we profiled genome-wide transcriptional changes by RNAseq 40 h after shRNA against TFAP4 was induced." (PMID 29880876, 2018). "Mechanistically, silencing TFAP4 induces neuroblastoma differentiation, as evidenced by increased neurite outgrowth and upregulation of neuronal markers." (PMID 29880876, 2018). "We demonstrate that TFAP4 is a direct target of MYCN in neuroblastoma cells, and that its expression and activity strongly negatively correlate with neuroblastoma patient survival." (PMID 29880876, 2018). "Mechanistically, we observed that in MYCN-amplified neuroblastoma cells, silencing of TFAP4 induces neurite outgrowth and upregulation of the neuronal marker GAP43." (PMID 29880876, 2018). "Taken together, these data indicate that both PRPS2 and SDC1 are co-operatively regulated by both MYCN and TFAP4 in neuroblastoma cells." (PMID 27448979, 2016). "Taken together, these data suggest that TFAP4 is required for the MYCN-driven neuroblastoma migration phenotype." (PMID 27448979, 2016). "siRNA-mediated suppression of TFAP4 in MYCN-expressing neuroblastoma cells led to inhibition of cell proliferation and migration." (PMID 27448979, 2016). "Microarray analysis identified genes regulated by both MYCN and TFAP4 in neuroblastoma cells, including Phosphoribosyl-pyrophosphate synthetase-2 (PRPS2) and Syndecan-1 (SDC1), which are involved in cancer cell proliferation and metastasis." (PMID 27448979, 2016). "The remaining genes found to be negatively regulated by MYCN and TFAP4, appear to be largely uncharacterised in cancer and their functions in neuroblastoma require investigation." (PMID 27448979, 2016). "In this study, we have demonstrated that TFAP4 is a direct transcriptional target of MYCN in neuroblastoma and that high levels of this transcription factor are associated with poor clinical outcome in this disease." (PMID 27448979, 2016). "Collectively, these data indicate that TFAP4 is a direct transcriptional target of MYCN in neuroblastoma." (PMID 27448979, 2016). "TFAP4 knockdown selectively hinders MYCN-elicited neuroblastoma growth both in vitro and in vivo." (PMID 34983307, 2022). "Taken together, our results demonstrate that TFAP4 is a key regulator of MYCN-amplified neuroblastoma and may represent a valuable novel therapeutic target." (PMID 29880876, 2018). "As a result, TFAP4 may play additional oncogenic roles in MYCN-amplified neuroblastoma tumorigenesis." (PMID 29880876, 2018). "Taken together, we propose a model that posits that, in MYCN-amplified neuroblastoma, high levels of MYCN upregulate the master regulator TFAP4, which in turn activates downstream oncogenic signaling pathways to promote cell cycle progression and inhibit neuroblastoma differentiation." (PMID 29880876, 2018).
neuroblastoma (continued). "Here, by integrating evidence from a whole-genome shRNA library screen and the computational inference of master regulator proteins, we identify transcription factor activating protein 4 (TFAP4) as a critical effector of MYCN amplification in neuroblastoma, providing a novel synthetic lethal target." (PMID 29880876, 2018). "In this study, the relevance of TFAP4 in the context of MYCN-driven neuroblastoma was investigated." (PMID 27448979, 2016). "The nuclear receptor NR1D1 has been shown to correlate with MYCN amplification in NB patients and TFAP4 inhibition leads to differentiation of MYCN-amplified neuroblastoma cells, supporting the validity of the inferred target genes." (PMID 38702304, 2024). "However, these oncogenic properties of TFAP4 were found in solid cancers, such as breast cancer, colorectal carcinoma, gastric cancer, neuroblastoma and certain others, and the role of TFAP4 in haematological malignancies has only been investigated in one study to date." (PMID 36894688, 2023). "We next investigated whether TFAP4 promotes cell growth in MYCN-amplified neuroblastoma." (PMID 27448979, 2016). "This analysis identified transcriptional factor activating protein 4 (TFAP4) as the top synthetic lethal candidate and MYCN-amplified neuroblastoma subtype MR." (PMID 29880876, 2018). "We further validated synthetic lethality of TFAP4 with MYCN amplification in vitro and in vivo in a range of neuroblastoma cell lines." (PMID 29880876, 2018). "We demonstrate that TFAP4 functions to promote proliferation and inhibit differentiation in MYCN-amplified neuroblastoma." (PMID 29880876, 2018). "Assessing the regulation of TFAP4 by MYCN/MYC, we found that high TFAP4 expression correlates with high MYCN or MYC expression in neuroblastoma cell lines and in the TARGET cohort of patients." (PMID 29880876, 2018). "Here, we demonstrate that TFAP4 is a direct target of MYCN, and that its expression is significantly upregulated in stage 4 MYCN-amplified neuroblastoma." (PMID 29880876, 2018). "Following this, we performed transient overexpression of TFAP4 in two neuroblastoma cell lines, SH-SY5Y and SK-N-FI which have relatively low levels of endogenous TFAP4." (PMID 27448979, 2016). "In particular, we have identified PRPS2 and SDC1 as genes that are positively regulated by both MYCN and TFAP4, and which represent novel candidate therapeutic targets for MYCN-driven neuroblastoma." (PMID 27448979, 2016). "Thus, TFAP4 is an attractive therapeutic target, as it is both synthetically lethal and a master regulator for MYCN-amplified neuroblastoma." (PMID 29880876, 2018). "Collectively, the present data do not suggest TFAP4 has a major role in the EMT phenotype of neuroblastoma." (PMID 27448979, 2016). "Furthermore, TFAP4 and MYCN co-operatively regulate a defined subset of genes to drive cell proliferation and migration in MYCN-driven neuroblastoma cells." (PMID 27448979, 2016). "To confirm the role of TFAP4 in neuroblastoma cell migration, we next performed cell migration assays after transiently overexpressing TFAP4 in MYCN non-amplified cell lines (SH-SY5Y and SK-N-FI), which express relatively low levels of both MYCN and TFAP4." (PMID 27448979, 2016). "Although SNAIL and CDH1 were not identified in our RNAseq analysis, it is possible that TFAP4 regulates a different set of EMT effectors and may restrict differentiation of MYCN-amplified neuroblastoma by this mechanism as well." (PMID 29880876, 2018). "Notably, TFAP4 did not regulate any genes in an antagonistic direction to MYCN in this subset of genes, suggesting that these two transcription factors cooperatively regulate specific target genes that play critical roles in the development of the aggressive phenotype of neuroblastoma." (PMID 27448979, 2016).
colorectal cancer (9 papers, 2016 to 2024). A primary or metastatic malignant neoplasm that affects the colon or rectum. "For examples, miR-302c attenuates cell EMT and metastasis through decreasing TFAP4 expression in colorectal cancer." (PMID 34141611, 2021). "Recently, TFAP4 overexpression was reported to confer worse prognosis in various malignancies, such as gastric cancer, colorectal cancer, prostate cancer, and non-small-cell lung carcinoma." (PMID 31281549, 2019). "In colorectal cancer, TFAP4 was found to be required for MYC-induced EMT, migration, and invasion providing strong evidence for this transcription factor being a new regulator of EMT contributing directly to colorectal cancer metastasis." (PMID 27448979, 2016). "TFAP4 has been shown to be a mediator of epithelial–mesenchymal transition (EMT) in colorectal cancer." (PMID 27448979, 2016). "miR-302 c targets TFAP4 to frustrate colorectal cancer metastasis and EMT." (PMID 34983307, 2022). "Similarly, TFAP4 overexpression has the potential to elicit colorectal carcinoma (CRC) and can function as an indicator of poor prognosis." (PMID 34983307, 2022). "High TFAP4 expression predicts poor outcomes in colorectal cancer patients." (PMID 34141611, 2021). "TFAP4 also promoted metastasis by regulating EMT in colorectal cancer." (PMID 31281549, 2019). "In addition, elevated TFAP4 expression significantly correlates with tumor progression and poor prognosis in a number of malignancies, including colorectal cancer, gastric cancer and non-small cell lung cancer." (PMID 27448979, 2016). "Moreover, miR-302c repressed EMT and metastasis via targeting TFAP4, and it might serve as a potential prognostic factor and therapeutic target for colorectal cancer." (PMID 37077419, 2023). "Protein factors that could regulate transcription of SMAD4-213 via AnnoLnc2 predicted binding sites upstream of/overlapping TSS that are expressed in colorectal cancer are CDX2, CEBPB, ELF1, NCOA1, NCOR1, NCOR2 and TFAP4." (PMID 39132157, 2024). "Recently, there has been increasing evidence that TFAP4 plays important roles in human cancer development and progression and in particular, it has been found to be a direct inducer of epithelial–mesenchymal transition (EMT) that contributes to metastatic processes in colorectal cancer." (PMID 27448979, 2016).
hepatocellular carcinoma (7 papers, 2019 to 2022). A malignant tumor that arises from hepatocytes. "Mainly TFAP4 was extremely cell type-specific in stellate 2, a gene that promotes tumorigenic capability and activates the Wnt/β-catenin pathway in hepatocellular carcinoma in previous studies." (PMID 35465320, 2022). "TFAP4 also promotes metastasis of hepatocellular carcinoma by activating PI3K/AKT signaling pathway." (PMID 34503278, 2021). "The current study was performed to quantify TFAP4 expression as well as to further determine its potential prognostic value and functional role in patients with hepatocellular carcinoma (HCC)." (PMID 31281549, 2019). "The TF TFAP4 induces the PI3K/AKT pathway activation to potentiate cell metastasis in hepatocellular carcinoma (HCC)." (PMID 34721660, 2021).
gastric cancer (6 papers, 2013 to 2023). A primary or metastatic malignant neoplasm involving the stomach. "TFAP4 has been reported to be upregulated in multiple tumor types, including colorectal and gastric carcinoma, which suggests that TFAP4 has an oncogenic role in cancer pathogenesis and progression." (PMID 31552102, 2019). "In addition, elevated TFAP4 activates the lncRNA TRERNA1 to facilitate gastric cancer cell migration and invasion." (PMID 35001801, 2022). "TFAP4 overexpression facilitates the malignant behaviors of gastric cancer cells." (PMID 34141611, 2021). "The other component comprises several circuits involving miR-17, miR-195 and miR-497 together with NF1 (a hypoxia-activated gene), TFAP4 (another cancer gene with prognostic importance in gastric carcinoma), MYC and HNF1A, and common target genes, which can mainly be classified as cancer genes." (PMID 23987127, 2013).
breast carcinoma (4 papers, 2016 to 2023). "Here, we analyzed the role of the c-MYC-induced TFAP4/AP4 gene in this context using a genetic approach in MCF-7 breast cancer cells." (PMID 36831504, 2023). "TFAP4 has been shown to repress the cell cycle checkpoint gene CDKN1A in a breast cancer cell line MCF7." (PMID 29880876, 2018).
colon carcinoma (3 papers, 2022 to 2025). "For example, cucurbitacin regulates the miR-371b-5p/TFAP4 axis, causes senescence, and inhibits colon cancer progression in colon cancer cells." (PMID 39188951, 2024). "Other studies showed that CurE was able to chemo-sensitize colon tumor cells by regulating TFAP4/Wnt/beta-catenin signaling and inhibit the proliferation of pancreatic adenocarcinoma cells by modulating STAT3 signaling." (PMID 36184616, 2022).
liver cancer (3 papers, 2022 to 2023). An epithelial or non-epithelial malignant neoplasm that arises from the liver. "Hyperactivation of TFAP4 has been observed in various human malignancies (e.g., intestinal, lymphoid and liver cancer)." (PMID 37033943, 2023). "miR-373-3p is downregulated and transcription factor-activating enhancer-binding protein 4 (TFAP4) is upregulated in liver cancer tissues." (PMID 36835100, 2023). "TFAP4 initiates the PI3K/AKT pathway to step up liver cancer development." (PMID 34983307, 2022). "TFAP4 activates the Wnt/β-catenin pathway to exert its carcinogenic function in liver cancer." (PMID 34983307, 2022). "Upregulating miR-373-3p triggers apoptosis in liver cancer cells by downregulating AKT and TFAP4, which is reversed by TFAP4 overexpression." (PMID 36835100, 2023). "TFAP4 activates the PI3K/AKT signal pathway, hence boosting tumor invasion and metastasis in liver cancer." (PMID 34983307, 2022).
non-small cell lung carcinoma (3 papers, 2019 to 2022). A group of at least three distinct histological types of lung cancer, including non-small cell squamous cell carcinoma, adenocarcinoma, and large cell carcinoma. "For instance, miR-608 represses TFAP4’s expression to boost non-small cell lung cancer apoptosis." (PMID 34983307, 2022).
glioma (2 papers, 2021 to 2022). A benign or malignant brain and spinal cord tumor that arises from glial cells (astrocytes, oligodendrocytes, ependymal cells). "LncRNA LINC00520 sponges miR-520f-3p by targeting TFAP4 to promote the progression of glioma malignancy." (PMID 34141611, 2021). "In addition, transcription factors are also involved in the regulation of LINC00520, including SP1 in NSCLC, TFAP4 in glioma, and STAT3 in BC." (PMID 35309319, 2022). "LIN00520 can be upregulated by SP1 in NSCLC, TFAP4 in glioma, and STAT3 in BC." (PMID 35309319, 2022). "In gliomas, TFAP4-66aa-uORF inhibits the TFAP4/LINC00520/miR-520f-3p feedback loop by directly inhibiting TFAP4 expression, thereby attenuating glioma malignancies." (PMID 35309319, 2022).
liver fibrosis (2 papers, 2025). "TFAP4, predominantly recognized as an oncogene, has recently been implicated in exacerbating liver fibrosis and tissue inflammation in mice by promoting the activation of the STING signaling pathway." (PMID 41158511, 2025). "Recent studies further support the pro-fibrotic role of TFAP4, showing its activation of NK-1R in renal fibrosis and STING signaling in liver fibrosis." (PMID 40612272, 2025).
lung carcinoma (2 papers, 2019 to 2020). "Although TFAP4 has been studied in other cancers, the oncogenic mechanism and function of TFAP4 in lung cancer are not clearly understood." (PMID 31552102, 2019).
lymph node metastasis (2 papers, 2019 to 2023). "In prostate carcinoma, TFAP4 was strongly elevated and associated with lymph node metastasis and GS." (PMID 36891298, 2023). "Moreover, high expression of TFAP4 was correlated with the clinical index of lymph node metastasis." (PMID 31552102, 2019).